BRAF (B-Raf proto-oncogene, serine/threonine kinase)
Diseases named in the same sentence as BRAF in open-access papers (continued):
Sharing a sentence is not in itself a finding about the gene and the disease.
brain tumors (continued). "Recently, aberrant methylation of MLH1, MGMT and MSI were shown to be associated with mutations in genes such as BRAF, RAS and IDH1 in colon and brain tumours." (PMID 23414134, 2013). "Activating mutations of the serine threonine kinase v-RAF murine sarcoma viral oncogene homologue B1 (BRAF), most commonly of the V600E type, are found in a wide range of human neoplasms including primary and secondary brain tumors." (PMID 22385786, 2012). "The suppression of autophagy with CQ was able to improve the responses of the cultured brain tumor cells resistant to BRAF blockers to chemotherapy with MEK inhibitor Trametinib and, more importantly, reduce the metastases of brain glioblastoma in patients with BRAF mutations." (PMID 38256019, 2024). "In-depth studies revealed that alterations of the V-Raf murine sarcoma viral oncogene homolog B (BRAF) could be shared by different brain tumour types." (PMID 36158392, 2022). "These BRAF liquid biopsy assays have shown promise for prognostication and monitoring treatment response and disease progression, but they have been relatively limited in their application to CNS metastasis and primary brain tumors." (PMID 33799709, 2021). "Importantly, recent study showed that BRAF/TERT promoter double-mutated brain tumor cells were sensitive to YK-4-279 treatment, providing a therapeutic opportunity to manage brain tumor patients harboring both BRAF and TERT mutations." (PMID 34221969, 2021). "To date, there are no available data investigating whether MAPK-inhibitors may affect seizure control in BRAF-activated brain tumours with BTRE." (PMID 34360713, 2021). "Our study demonstrates the feasibility of plasma-based brain tumor biomarker detection and paves the path for liquid biopsy based molecular profiling for diagnosis and longitudinal monitoring in patients with primary and metastatic BRAF V600E mutant brain tumors." (PMID 33799709, 2021). "Published case reports of brain tumors treated with BRAF/MEK-i." (PMID 35155453, 2021). "These tumors have been found to be negative for IDH variants, BRAF variants and BRAF fusions, which are changes commonly found in low grade brain tumors." (PMID 31046843, 2019). "This highlights the important role of BRAF alterations in oncogenic signaling in brain tumors." (PMID 31181803, 2019). "The VE-BASKET study investigating the efficacy of the BRAF inhibitor vemurafenib against BRAF V600E-mutant cancers demonstrated that efficacy varied by histologic subtypes in patients with BRAF V600E-mutant brain tumors, suggesting that some BRAF V600E-mutant tumors have multiple concurrent drivers." (PMID 31345255, 2019). "Autophagy inhibition improves chemosensitivity in BRAF(V600E) brain tumors." (PMID 30443293, 2018). "The skin lesion, but not the brain tumor, had a BRAF mutation (c.1397G > T; p.G466V)." (PMID 25330907, 2014). "BRAF/MEK targeted therapies are undergoing clinical testing for BRAF-mutant glioneuronal and other brain tumors, with early evidence suggesting clinically-significant anti-tumor activity." (PMID 36966348, 2023). "Moreover, next-generation sequencing (NGS) of tumor specimens has enabled identification of other mutations in the BRAF gene in primary brain tumors, but many of these do not respond to FDA-approved RAF inhibitors and may in fact progress more rapidly." (PMID 31466300, 2019).
brain tumors (continued). "Interestingly, BRAF activation in human neural stem and progenitor cells not only promotes tumor growth, but also subsequently causes oncogene-induced senescence in some low-grade brain tumors." (PMID 31181803, 2019). "In a recent study in brain tumors bearing BRAFV600E, autophagy inhibition by Chloroquine sensitize cancer cells to BRAF inhibitor vemurafenib." (PMID 30427914, 2018). "In addition to being potent against KIAA1549:BRAF, tovorafenib is brain-penetrant, and as such, it is being evaluated in PLGA, a brain tumor that is frequently driven by the KIAA1549:BRAF fusion." (PMID 36963492, 2023). "This explains why, despite the described active export of BRAF/MEKis, these medications have been shown to have good, albeit varied, clinical efficacy in MAPK pathway–altered intracranial melanoma metastases and primary brain tumors." (PMID 37124503, 2023). "In this review, we summarize the current evidence on targeted therapies with focus on v-RAF Murine Sarcoma Viral Oncogene Homolog B1 (BRAF), isocitrate dehydrogenase 1 (IDH) and neurotrophic tyrosine receptor kinase (NTRK) fusion in a precision medicine approach for adult primary brain tumors." (PMID 35158978, 2022). "Additionally, targeted therapies (i.e., BRAF, MEK and TRK inhibitors) have demonstrated promising activity in pediatric brain tumors." (PMID 34168987, 2021). "Alterations in the v-raf murine sarcoma viral oncogene homolog B (BRAF) protein, the upstream activator of the MEK-ERK signalling cascade, are frequently found in both, paediatric and adult brain tumours, but extremely rare in GB, present in only 1–2% of these tumours." (PMID 32366879, 2020). "No BRAF exon 15 and EGFR exons 3 and 7 mutations were identified in 54 and 31 assessed primary brain tumors, respectively." (PMID 27454254, 2016). "In fact, to the best of our knowledge, there is no active study regarding brain drug delivery of BRAF and MEK inhibitors in primary pediatric brain tumors." (PMID 36077798, 2022). "Unlike BRAF-altered adult malignancies or high-grade brain tumors, no PLGG patient-derived cell lines harboring BRAF-fusions have been successfully isolated or characterized." (PMID 29156677, 2017).
thyroid nodule (99 papers, 2006 to 2026). A small circumscribed mass in the THYROID GLAND that can be of neoplastic growth or non-neoplastic abnormality. "Despite their low prevalence in ITNs (4.2%), the positive predictive value of BRAF V600E mutations is high—close to all BRAF V600E mutant thyroid nodules represent PTC." (PMID 40075589, 2025). "To address these issues, we conducted a prospective study to validate the preoperative detection of BRAF V600E mutations in thyroid nodules using the ThyroSCAN PanelChip." (PMID 40310607, 2025). "Inclusion criteria comprised patients aged ≥ 18 years with thyroid nodules ≤ 1 cm, documented BRAF V600E mutation and AF results, and available surgical pathology reports." (PMID 40805249, 2025). "This study not only enhances the understanding of preoperative molecular testing for thyroid nodules but also contributes to the report of the first case of FTC with a novel BRAF (V600_K601insNTV) mutation presenting as preoperative BRAF V600E false-positive." (PMID 40310607, 2025). "The study concluded that utilizing both US characteristics and BRAF V600E mutation status enhances the diagnostic accuracy for AUS/FLUS thyroid nodules." (PMID 40970023, 2025). "By reviewing its sensitivity, specificity, and clinical and financial impact, we seek to clarify the role of BRAF mutation analysis in improving the risk stratification and management of patients with indeterminate thyroid nodules." (PMID 40970023, 2025). "The BRAF V600E mutation in thyroid nodules with AUS has significant diagnostic implications for PTC." (PMID 40970023, 2025). "In PTC, both tall cell and hobnail subtypes, associated with worse patient prognosis, have been linked with BRAF V600E-positive thyroid nodules." (PMID 40805249, 2025). "In comparison with BRAF V600E mutant thyroid nodules, thyroid nodules with non-V600E BRAF mutations have a lower risk of malignancy, and very low risk of aggressive or ATA high-risk malignancy." (PMID 40075589, 2025). "With the analysis of genetic profiles in thyroid nodules, BRAF V600E, TERT mutations, and gene fusions were included in the 6-gene test panel." (PMID 40586006, 2025). "The study concluded that utilizing both US characteristics and BRAF V600E mutation status enhanced the diagnostic accuracy for AUS/FLUS thyroid nodules." (PMID 40970023, 2025). "The 22-gene mutation assay showed a genetic profile of thyroid nodules in the Chinese populations with a high frequency of BRAF and RAS mutations." (PMID 40586006, 2025). "This study represents the first preoperative investigation of BRAF V600E mutations in thyroid nodules conducted in Taiwan." (PMID 40310607, 2025). "This study established an integrated deep learning model, BrafSwinT, to predict the BRAF V600E mutation status in PTC patients based on gray-scale US images of the thyroid nodules and basic clinical data." (PMID 40395668, 2025). "In this study, the frequency of the BRAF V600E mutation in malignant thyroid nodules was 70.22% (158/225), which was consistent with the results reported in the Chinese population (63.6∼87.7%) and higher than that in the Western population (30∼70%)." (PMID 40586006, 2025). "Of note, Bethesda category V and VI thyroid nodules have a strong correlation with BRAF V600E mutations, whereas intermediate thyroid nodules categorized as Bethesda III and IV are associated with H, K, or NRAS or EIF1AX mutations, CNAs, or GEP." (PMID 39766147, 2024). "BRAF mutations have been found in 20.3% (337/1654) of thyroid nodules, including classic (p.V600E) mutation in 19.2% (317/1654) of samples and non-V600E variants in 1.1% of cases (19/1654)." (PMID 36835466, 2023).
thyroid nodule (continued). "Univariate analysis revealed that the differences in age, maximum diameter of thyroid nodules, capsular invasion, and BRAF V600E mutation were statistically significant between the two groups (P < 0.05)." (PMID 36750791, 2023). "The statistically significant indicators (age, maximum diameter of thyroid nodules, capsular invasion and BRAF V600E mutation) from the multifactorial analysis were used to construct a nomogram prediction model for CLNM." (PMID 36750791, 2023). "We also explored the diagnostic efficiency of US-FNAB and proto-Oncogene Proteins B-raf V600E (BRAF V600E) mutation in macro-calcified thyroid nodules evaluation." (PMID 37194091, 2023). "Next-generation sequencing allowed the detection of BRAF non-V600E mutations in 1.2% of 1654 thyroid nodules." (PMID 36835466, 2023). "In further analyses, in addition to the BRAF V600E mutation, we also found that age, maximum diameter of thyroid nodules, and capsular invasion were also independent risk factors for CLNM." (PMID 36750791, 2023). "Molecular techniques such as TsV3 enhance the management of thyroid nodules by identifying mutations highly specific for malignancy such as BRAF V600E, RET or TERT, ultimately reducing the number of diagnostic thyroidectomies required." (PMID 36612045, 2022). "The study was conducted to investigate the correlation between the ultrasonographic appearance of a thyroid nodule and the BRAF V600E mutation." (PMID 35356255, 2022). "The detection of mutations in the BRAF gene can assist in differentiating among thyroid nodules, but there are cost and time limitations associated with BRAF testing." (PMID 36160023, 2022). "There were few predictive models of BRAF gene mutations in thyroid nodules based on ultrasound as well as clinical parameters." (PMID 36160023, 2022). "Thyroid nodules with GEAs are significantly more likely to have aggressive features if they are associated with the BRAF V600E mutation." (PMID 36612045, 2022). "Our study showed that the rate of BRAF mutations in patients with thyroid nodules alone was 49.82% (137/275)." (PMID 36160023, 2022). "Our results also showed that microcalcification was the specific manifestation in thyroid nodules with BRAF mutations." (PMID 36160023, 2022). "We demonstrated in this study that both NGS and MS are effective methods for detecting BRAF V600E mutations in FNA biopsy samples of patients with thyroid nodules, with a strong inter-rater agreement, high specificity, and high PPV." (PMID 35992139, 2022). "In particular, identifying a BRAF V600E mutation pre-operatively can help clinicians recognize potentially high-risk thyroid nodules and offer appropriate patient counseling and management." (PMID 36612045, 2022). "In this study, we applied ddPCR to detect the BRAF V600E mutation in FNA samples from thyroid nodules and compared its sensitivity with that of Sanger sequencing." (PMID 35392249, 2022). "Our study used retrospective data collected from patients with thyroid nodules to develop a diagnostic nomogram for assessing the presence of mutations in the BRAF gene." (PMID 36160023, 2022). "Molecular tests can rule in cancer for indeterminate thyroid nodules with highly specific mutations for cancer, such as BRAF and RET/PTC." (PMID 35197932, 2022). "The diagnostic accuracy of thyroid nodule can be improved by combining mutations in the B-Raf proto-oncogene serine/threonine kinase (BRAF) with FNA." (PMID 36160023, 2022). "One example is that if BRAF V600E is found in cells obtained from FNA of a thyroid nodule, even within low mutated allele frequency, the nodule is considered malignant and surgery is indicated based on this finding." (PMID 34135377, 2021). "This study postulates that molecular testing for BRAF V600E can prove to be an important approach to identifying high-risk small thyroid nodules and therefore guide initial surgical management." (PMID 34742355, 2021).
thyroid nodule (continued). "A recent study reveals that TIRADS classification can be used as a clinical parameter for deciding the BRAF mutation test in thyroid nodules with AUS/FLUS cytology." (PMID 35047385, 2021). "In one multifocal PTC in our study, the NTRK fusion gene was found in one thyroid nodule and the BRAF V600E mutation in another." (PMID 33923728, 2021). "Previous reports have suggested that up to 13.3% (2 out of 15) of thyroid nodules determined to be benign on final pathology can harbor BRAF (V600E) mutations." (PMID 34475951, 2021). "Adding BRAF V600E‐mutation analysis to the diagnostic workup of thyroid nodules is only rational when the frequency of the BRAF V600E‐mutation is sufficiently high in PTCs in the local population." (PMID 34156770, 2021). "The purpose of this study was to determine the ability to detect BRAF (V600E) mutations in the plasma of patients with thyroid nodules, with the goal of distinguishing between benign and malignant nodules." (PMID 34475951, 2021). "The Bio‐rad QX200TM ddPCR was shown to improve diagnostic accuracy for detecting the BRAF V600E mutation by 17% compared to cytopathology alone in thyroid nodules FNA samples." (PMID 32671901, 2020). "Although older PTC patients were more likely to have the BRAF V600E mutation, BRAF V600E was more prevalent in younger individuals with thyroid nodules detected with ddPCR; both correlate significantly with aging (both P for trend < 0.05)." (PMID 32671901, 2020). "It showed a better performance than ARMS‐PCR in BRAF V600E mutation detection on thyroid nodule FNA specimens, which is in line with a previous study." (PMID 32671901, 2020). "The BRAF V600E mutation testing on FNA specimens from thyroid nodules greatly improves diagnostic accuracy." (PMID 32671901, 2020). "We performed an observational study in order to describe the frequency of the BRAF 1799T>A mutation in Mexican mestizo patients with thyroid nodules, a scarcely studied ethnic group with large populations." (PMID 29808165, 2018). "His study provided personalized and quantified information of the probability of PTC and also emphasized the significance of preoperative BRAF mutation analysis in indeterminate thyroid nodules." (PMID 27654865, 2016). "The prediction model mentioned in the study provided personalized and quantified information regarding the probability of PTC and emphasized the significance of preoperative BRAF mutation analysis in indeterminate thyroid nodules." (PMID 27654865, 2016). "Of the 2549 thyroid nodules positive for the BRAF mutation, 2530 (99.3%) of them were PTC and the remaining 19 nodules were eventually diagnosed as 2 FTCs, 2 MTCs, and 15 BN conditions." (PMID 26020381, 2015). "Based on this finding, clinicians should perform routine BRAF mutation analysis in indeterminate thyroid nodules because of the HR of PTC in BRAF-positive indeterminate thyroid nodules." (PMID 26020381, 2015). "We strongly recommend preoperative evaluation of the BRAF V600E mutation in indeterminate thyroid nodules." (PMID 26020381, 2015). "The presence of BRAF mutation in cytology material obtained from FNAB of thyroid nodule indicates the necessity of surgical treatment." (PMID 24987460, 2014). "BRAF mutation testing would thus be a very informative and useful tool in the management of thyroid nodules and cancers." (PMID 24588959, 2014). "BRAF mutational analysis is commonly used to assess the malignancy of thyroid nodules but unfortunately it still leaves indeterminate diagnoses." (PMID 22233760, 2012). "The application of BRAF/V600E mutation analysis in FNAB specimens is more effective for thyroid nodules with malignant echographic features as compared with nodules without malignant echographic features." (PMID 22654559, 2011). "In contrast, this study used a simple and efficient qPCR chip to assess whether FNA specimens from thyroid nodules contain the BRAF V600E mutation, along with four other gene mutations." (PMID 40310607, 2025).